MIR133A1HG (MIR133A1 host gene)
Synonyms: MIR1-2HG
Gene: Long non-coding RNA gene on chromosome 18 (21,825,487 to 21,831,539, reverse strand). Ensembl gene ENSG00000265142.
Gene Ontology:
Biological process: miRNA-mediated post-transcriptional gene silencing
Cellular component: RISC complex